ATP5MG (ATP synthase membrane subunit g)
Description:
Subunit g, of the mitochondrial membrane ATP synthase complex (F(1)F(0) ATP synthase or Complex V) that produces ATP from ADP in the presence of a proton gradient across the membrane which is generated by electron transport complexes of the respiratory chain. ATP synthase complex consist of a soluble F(1) head domain - the catalytic core - and a membrane F(1) domain - the membrane proton channel. These two domains are linked by a central stalk rotating inside the F(1) region and a stationary peripheral stalk. During catalysis, ATP synthesis in the catalytic domain of F(1) is coupled via a rotary mechanism of the central stalk subunits to proton translocation (Probable). In vivo, can only synthesize ATP although its ATP hydrolase activity can be activated artificially in vitro (By similarity). Part of the complex F(0) domain.
Synonyms: ATP5L; ATP5JG
Tractability: Small molecule: a structure with a bound ligand is known. PROTAC: ubiquitination databases record sites on it.
Gene: Protein-coding gene on chromosome 11 (118,401,346 to 118,433,278, forward strand). Ensembl gene ENSG00000167283.
Subcellular location: Mitochondrion; Mitochondrion inner membrane
Subcellular location (Human Protein Atlas): Mitochondria; Principal piece
Pathways (Reactome):
Metabolism: Formation of ATP by chemiosmotic coupling
Metabolism of proteins: Mitochondrial protein degradation
Organelle biogenesis and maintenance: Cristae formation
Gene Ontology:
Molecular function: protein binding; proton-transporting ATP synthase activity, rotational mechanism; proton transmembrane transporter activity
Biological process: proton motive force-driven mitochondrial ATP synthesis; proton motive force-driven ATP synthesis; proton transmembrane transport
Cellular component: mitochondrion; proton-transporting ATP synthase complex; mitochondrial inner membrane
Genetic constraint (gnomAD): Loss-of-function variants: 7 observed, 11.7 expected, observed/expected ratio (o/e) 0.6, 90% interval 0.34 to 1.12. The upper end of that interval is the gene's LOEUF score, 1.12, which puts it in group 4 of 6, group 1 being the genes least tolerant of losing a copy. Missense variants: 107 observed, 119.53 expected, observed/expected ratio (o/e) 0.9, 90% interval 0.76 to 1.05. Synonymous variants: 50 observed, 45.61 expected, observed/expected ratio (o/e) 1.1, 90% interval 0.87 to 1.39.
Homologues: Orthologues: chimpanzee ATP5MG (100% identical), dog ATP5MG (90% identical), pig ATP5MG (86% identical), mouse Atp5mg (83% identical), mouse Atg5lrt (76% identical), rat Atp5mg (74% identical), zebrafish atp5l (71% identical), Drosophila melanogaster ATPsynG (53% identical), Drosophila melanogaster ATPsynGL (43% identical), Caenorhabditis elegans asg-1 (38% identical), Caenorhabditis elegans asg-2 (35% identical). Paralogues in human: ATP5MGL (86% identical).
Diseases named in the same sentence as ATP5MG in open-access papers:
ATP5MG is named in the same sentence as 17 diseases in open-access papers, as found by Europe PMC text mining. Sharing a sentence is not in itself a finding about the gene and the disease. The quoted sentences say what the papers report.
Stroke (1 paper, 2024). Sudden impairment of blood flow to a part of the brain due to occlusion or rupture of an artery to the brain. "Core genes (UQCRQ, USMG5 [ATP5MD], COX6C, NDUFB3, ATP5L [ATP5MG], COX7C, NDUFA1, NDUFA4) were highly expressed in septic shock and stroke samples." (PMID 39655053, 2024).
infection (1 paper, 2022). The state of being infected such as from the introduction of a foreign agent such as serum, vaccine, antigenic substance or organism. "HIV infection was further analyzed, and the involvement of ATP5MG in infection events with 21 terms was upheld." (PMID 35935642, 2022).
ATP5MG also shares sentences with these, for which no sentence is quoted: tumor (3 papers); myocarditis (2); Alzheimer disease (1); asthma (1); B-cell lymphomas (1); blood cancer (1); breast tumor (1); cancer (1); cyst (1); diabetes (1); dyslipidemia (1); hematological disease (1); myocardial infarction (1); myocardial ischemia (1); neuroblastoma (1).